CXCL5 (C-X-C motif chemokine ligand 5)
Diseases named in the same sentence as CXCL5 in open-access papers (continued):
Sharing a sentence is not in itself a finding about the gene and the disease.
pulmonary fibrosis (10 papers, 2021 to 2025). Chronic progressive interstitial lung disorder characterized by the replacement of the lung tissue by connective tissue, leading to progressive dyspnea, respiratory failure, or right heart failure. "Aerobic exercise for 4 weeks ameliorated silica-induced lung fibrosis in mice through the inhibition of the IL-17A/CXCL5/Chemokine (C-X-C motif) Receptor 2 (CXCR2) axis." (PMID 39796197, 2025). "Chemokines CXCL5 and CCL5 are known to play a role in leukocyte chemotaxis during inflammation of the lungs and CXCL5 has been associated with idiopathic pulmonary fibrosis." (PMID 37460469, 2023). "Although the mechanism that caused the fibrosis due to exposure to CL-PAA is uncertain, in previous reports, it was shown that pulmonary fibrosis was partly dependent on angiogenesis, suggesting that CXCL5 was an important angiogenic factor in idiopathic pulmonary fibrosis." (PMID 35062982, 2022). "Altogether, we consider that increased expression of CXCL5 may be involved in the development and persistence of pulmonary fibrosis by promoting EMT." (PMID 35062982, 2022). "CXCL5 levels are correlated with the number of neutrophils in BAL fluid, and increased CXCL5 levels in airspace may be associated with emphysematous lung manifestations in patients with pulmonary fibrosis." (PMID 39768150, 2024). "We previously reported that elevated expression of CXCL5 may promote epithelial to mesenchymal transition (EMT) and be involved in the onset and persistence of pulmonary fibrosis, and it is possible that those cytokines caused the onset and persistence of lung fibrosis in this experiment." (PMID 36459418, 2022). "Thus, moderate-intensity aerobic exercise (60 min/day, five times/week for 4 weeks) attenuates silica-induced lung fibrosis by inhibiting the TLR4-TNF-α, SRB-NLPR3, TGF-β1, and IL-17A/CXCL5/CXCR2 signaling pathways." (PMID 39796197, 2025). "Studies have demonstrated an imbalance in the levels of angiogenic chemokines (ELR+ CXC chemokines [CXCL5 and CXCL8]) and angiostatic chemokines (interferon-inducible ELR- CXC chemokines [CXCL9, CXCL10, CXCL11]) in animal models of pulmonary fibrosis and lung tissue from patients with IPF." (PMID 39418259, 2024). "Although neutrophil accumulation-inducing chemokines like IL-8 are increased in sarcoidosis, the percentage of neutrophils in the bronchoalveolar lavage remains low and is not correlated to CXCL8 or CXCL5 as in idiopathic pulmonary fibrosis." (PMID 35425769, 2022). "The data highlight the enhanced inducible cytokine CXCL5 involved in neutrophil recruitment, tissue remodeling and COPD, and placental growth factor (PGF) which is induced in the lung hyperoxia response, involved in macrophage polarization and angiogenesis, and exacerbates pulmonary fibrosis." (PMID 33613309, 2021). "The lack of changes in Cxcl13, Ccl11, Ccl19, Xcl1, and Cxcl5 mRNA levels may be due to differences in bleomycin-induced pulmonary fibrosis and IPF, although models of bleomycin-induced pulmonary fibrosis are the most common experimental models for investigating IPF." (PMID 37122736, 2023).
breast tumor (9 papers, 2013 to 2025). "CXCL5, which encodes for epithelial neutrophil-activating peptide (ENA-78), is up-regulated in breast tumors and plays a role in regulating neutrophil homeostasis, an essential component of innate immunity, and a major contributor to inflammation-associated tissue damage." (PMID 23991131, 2013). "Breast tumors produce various factors, such as G-CSF, granulocyte/macrophage stimulating factor (GM-CSF), IL-6, IL-1β, IL-17, TGF-β, C-X-C motif chemokine 2 (CXCL2; encoded by CXCL2), C-X-C motif chemokine 5 (CXCL5; encoded by CXCL5), and CCL2." (PMID 41550427, 2025). "Notably, resistin expression was found to positively correlate with CXCL5 expression in the breast tumor tissues of the patients." (PMID 36104403, 2022). "However, IL1R1, ILRAP, IL6ST, CXCL3, CXCL5, and CXCL6 gene expression was higher in normal adjacent tissue than in breast tumor tissue." (PMID 39201290, 2024). "Different studies indicated that various types of chemotherapy share the ability to promote the release of ELR+ CXC chemokines—CXCL1, CXCL2, CXCL3, CXCL5, CXCL7 and CXCL8 (depending on the study) —by myeloid cells, breast tumor cells and mesenchymal stem cells." (PMID 33585241, 2020). "However, IL1R1, ILRAP, IL6ST, CXCL3, CXCL5, and CXCL6 gene expression levels were higher in normal adjacent tissue than in breast tumor tissue indicating that the surrounding non-tumor tissue could also present an inflammation." (PMID 39201290, 2024).
ischemic stroke (9 papers, 2008 to 2024). A stroke disorder caused by obstruction of blood flow to the brain, due to thrombotic (local blood clot formation) or embolic (due to a blood clot or other material traveling from another site) event. "Recent studies have showed that CXCL5 and its receptors are implicated in congestive heart failure and ischemic stroke, making CXCL5 a candidate gene for potential future therapy strategies in cardiovascular diseases." (PMID 29530068, 2018). "Detrimental effects of CXCL5 have also been reported in ischemic stroke, where CXCL5 elevation in CSF was associated with brain infarct size." (PMID 26860080, 2016). "It was found that CXCL5 levels in cerebrospinal fluid of ischemic stroke patients increased rapidly, and CXCL5 levels were positively correlated with the volume of early brain CT hypodense areas." (PMID 39206161, 2024). "CXCL5 has been shown to be upregulated in ischemic stroke and this correlates positively with brain injury." (PMID 34359826, 2021). "Recent data have implicated CXCL5 and/or its receptors in congestive heart failure and ischemic stroke, making CXCL5 a candidate gene for other manifestations of CVD including ACS." (PMID 18769620, 2008). "I/R causes an increase in CXCL5 levels in the cerebrospinal fluid of ischemic stroke patients, which in turn leads to damage of human brain microvascular endothelial cells and blood-brain barrier disruption, and CXCL5 levels are positively correlated with the degree of early cerebral nerve injury." (PMID 39206161, 2024). "A recent paper reports CXCL5 (that binds with CXCR1 and CXCR2 and activates the p38 MAP kinase signaling pathways) to be upregulated in ischemic stroke." (PMID 36982232, 2023).
ovarian carcinoma (9 papers, 2015 to 2024). A malignant neoplasm originating from the surface ovarian epithelium. "CXCL5, secreted by ovarian cancer-associated mesothelial cells, has been demonstrated to have tumor-promoting properties." (PMID 36969851, 2023). "Some studies had found that ETS1 exosomes secreted by ovarian cancer cells induce the polarization of M2 macrophages, which overexpress CD163, IL-10, CCL2, CXCL5 and other immunosuppressive factors, and significantly stimulate the migration of ovarian cancer cells." (PMID 39539540, 2024). "In ovarian cancer, both CXCL5 and CCL2 are pro-metastatic cytokines." (PMID 36477408, 2022). "In addition, CXCL1, CXCL2, and CXCL5 (ENA-78) can stimulate cell proliferation and migration in ovarian cancer." (PMID 26414070, 2015). "Our results align with these findings and show that CXCL1, CXCL5, CXCL8, and CXCL11 are overexpressed in ovarian cancer." (PMID 36969851, 2023). "As in mouse MDSCs, MDSCs from human ovarian cancer ascitic fluid samples were attracted by CXCL1, CXCL2, and CXCL5, and a CXCR2 antagonist inhibited this migration." (PMID 29703902, 2018). "These exosomes are more readily absorbed by omental macrophages, are able to drive the polarization of macrophages toward the M2 phenotype, and upregulate the expression of CXCL5 and CCL2 in macrophages, thereby boosting metastasis and omental colonization in ovarian cancer." (PMID 36477408, 2022). "Compared with control exosomes, exosomes derived from ETS1-overexpressing ovarian cancer cells (LV-ETS1 Exos) stimulated the polarization of more macrophages toward the M2 phenotype (CD163 marker), as well as the production of more CXCL5 and CCL2 in macrophages, via integrin αvβ5/AKT/Sp1 signaling." (PMID 36477408, 2022).
prostate tumor (9 papers, 2019 to 2025). "The baseline and radiation-enhanced secretion of CXCL8 (and its orthologues CXCL1, CXCL2 and CXCL5) from PTEN-deficient prostate tumour epithelial cells exerts both autocrine and paracrine actions within the tumour microenvironment given the expression of CXCR1 and CXCR2 upon multiple cell types." (PMID 32743555, 2020). "Recently, it was reported that apoptosis-induced CXCL5 accelerates inflammation and growth of prostate tumor metastases in the bone." (PMID 31467637, 2019). "Additionally, sCD163 is specifically related to alternative “M2-type” macrophages, which are abundantly found in cancer, whereas CXCL5 protein expression levels are concordant with prostate tumor progression." (PMID 31500625, 2019). "Differential expression of CXCL5 and CCL23 was analyzed using immunohistochemistry in a representative cohort of prostate tumor tissues of AA and CA races." (PMID 37698493, 2023). "To assess if CXCL5 and CCL23 are differentially expressed in prostate tumors, we performed immunohistochemistry (IHC) in archival prostate tumor tissues of AA and CA races." (PMID 37698493, 2023). "For example, the apoptosis-induced chemokine CXCL5 and its receptor CXCR2 have been reported to accelerate inflammation and growth of prostate tumor metastases in bone." (PMID 31500625, 2019). "Immunostaining for CXCL5 and CCL23 in a representative cohort of archival prostate tissues displayed significantly higher CXCL5 in prostate tumors than in adjacent benign tissues, while CCL23 was non-detectable in most of the analyzed tumor tissues." (PMID 37698493, 2023). "Collectively, we show that Cxcl5, but not Cxcl9/10 from the stromal cells, is the major downstream effector of stromal Foxf2 in suppressing prostate tumor growth." (PMID 36369237, 2022).
Stroke (9 papers, 2012 to 2024). Sudden impairment of blood flow to a part of the brain due to occlusion or rupture of an artery to the brain. "Chemokines such as Cxcl5 and Ccr7 were also downregulated in both male and female stroke brains upon MMP-3 KO." (PMID 39000490, 2024). "Using available plasma samples from a single-center cohort study including subjects presenting with acute neurologic symptoms suggestive of stroke, we assayed plasma levels of IL-17B and CXCL5 using a custom Luminex assay." (PMID 36543124, 2022). "Increased levels of CXCL5 have been found in the CSF of patients at 24 h after stroke." (PMID 27635404, 2016). "In peri-infarct tissue 7 days after subcortical white matter stroke, endothelial CXCL5 expression is significantly increased in mice on HFD versus those on CFD as measured by the percentage of CXCL5+ voxels that co-localized with GLUT-1 within the peri-infarct tissue surrounding the stroke." (PMID 36543124, 2022). "Genes related to inflammation such as Ccl5, Cxcl5, Il1a, Tnfsf10, Nfkb1, Tnfrsf1b, Ccr7, Tnfrsf9, Ccl7, Il1b, Il6, and Ccl24 were also downregulated upon MMP-3 KO in male stroke brains." (PMID 39000490, 2024). "However, the expression of CCL2, CCL3, CCL4, CCL7, and CXCL2 was strongly increased after stroke, whereas CCL19, CCL20, and CXCL5 expression levels were not changed." (PMID 26640428, 2015).
viral infection (9 papers, 2013 to 2025). "In contrast, CXCL5, a gene associated with neutrophil activation and also present in network 4, was up-regulated following virus infection." (PMID 34244540, 2021). "In the transcriptome data, Il1b and Ptgs2 (encoding cyclooxygenase 2, COX‐2) showed higher elevation at almost all the time points post viral infection, while some other genes like Il6, Il12b, and Cxcl5 only showed significant elevation at 48 hpi." (PMID 38992966, 2025). "In this study, we generated an influenza (H1N1) infected CXCL5-knockout (CXCL5-/-) mouse model to elucidate the potential role of CXCL5 in viral infection-induced inflammatory pulmonary disease." (PMID 34868067, 2021). "Viral load detection showed that both the WT and CXCL5-/- reinfected mice with either H1N1 or H3N2 challenge remarkably restrained viral infection and replication." (PMID 34868067, 2021). "Interestingly, viral infection also leads to reduced production of CXCL5, CCL5, CCL3, and GM-CSF, which are mainly involved in the attraction and activation of granulocytes and monocytes, suggesting that SARS-CoV-2 actively inhibits the recruitment of leukocytes early in infection." (PMID 33670363, 2021). "Among the pro-inflammatory mediators, a significant increase in mRNA for CSF2, CSF3, CXCL2, CXCL5, IL6, IL8, and also IL1 and IL18 was observed 24 h after viral infection." (PMID 23723976, 2013). "Even though CLEC2.Fc was unable to inhibit virus infection and replication, CLEC2.Fc inhibited the expression of IL‐6, CXCL2, CXCL5, CCL2, and IP‐10 at day 3 and day 5 post‐infection, and the expression of TNF‐α, IFN‐γ, IL‐10, and CXCL1 was also suppressed at day 5 post‐infection (red columns)." (PMID 37211986, 2023). "Hierarchical clustering identified a distinctive innate immune signature in bite sites that was dominated by neutrophil-attracting chemokines (CXCL1, CXCL2, CXCL3, and CXCL5) and the cytokines IL-1β and IL-6, which were not significantly induced by virus infection alone." (PMID 27332734, 2016).
pancreatic ductal adenocarcinoma (8 papers, 2020 to 2025). An infiltrating adenocarcinoma that arises from the epithelial cells of the pancreas. "Analysis of online databases and tissue microarray staining in pancreatic ductal adenocarcinoma patients showed that elevated CXCL5 is a marker of poor prognosis." (PMID 41392310, 2025). "Among the CXCR2 ligands, CXCL5 demonstrated the highest expression levels in human pancreatic ductal adenocarcinoma." (PMID 38884019, 2024). "Western blot results showed that, compared to hTERT-HPNE, model genes including KRT7, KRT19, IGF2BP3, and CXCL5, were significantly increased in human pancreatic ductal carcinoma cell lines, PANC-1 and PL45." (PMID 37371833, 2023). "However, the relationships between CXCL5, immune cell infiltration and pancreatic ductal adenocarcinoma (PDAC) remain largely unknown." (PMID 32201508, 2020). "In particular, this refers to C-X-C motif ligand 5 (CXCL5, epithelial neutrophil-activating protein 78 (ENA78)) and CXCL8, which expression in pancreatic ductal adenocarcinoma tumors are the highest among CXCR2 ligands." (PMID 37408240, 2023).
Sepsis (8 papers, 2013 to 2024). Sepsis is defined as life-threatening organ dysfunction caused by a dysregulated host response to infection. "Examples of Hyper-Induced molecules include Cxcl5, a neutrophil chemoattractant that has been shown to limit the development of sepsis." (PMID 38157387, 2023). "It remains to be determined if the effect of IFN-γ on the transcription of CXCL-5 will be beneficial for sepsis patients." (PMID 23874546, 2013). "Loss of ALKBH5 did not alter the levels of CXCL12 and CXCL5 in the plasma, bone marrow or peritoneal lavage fluid of mice in the steady state or during sepsis." (PMID 38114747, 2024). "In addition, the Cxcl5 neutrophil recruiting chemokine, shown to play a role in suppression of sepsis, was identified as having a hyper-induced phenotype." (PMID 38157387, 2023). "In polymicrobial sepsis, the activation of the NFAT pathway led to an increase in the expression of chemokines (CXCL1, CXCL2 and CXCL5) and neutrophil migration and infiltration in the lung, whereas FK506 impaired central migration of neutrophils." (PMID 38242872, 2024).
autoimmune disease (7 papers, 2015 to 2025). A disorder resulting from loss of function or tissue destruction of an organ or multiple organs, arising from humoral or cellular immune responses of the individual to their own tissue constituents. "Therefore, we focused on CXCR1, the first chemokine receptor cloned in 1991, and its mouse ligand CXCL5/LIX, which has been shown to mediate cell migration and granule release in neutrophils in response to bacterial infections and autoimmune diseases." (PMID 37709757, 2023). "For instance, in the case of autoimmune diseases, such as multiple sclerosis or experimental autoimmune encephalomyelitis, neutrophils are known to be attracted by the release of CXCL1, CXCL2, and CXCL5, which are in turn stimulated by different molecules, such as IL-17 or IFN-γ." (PMID 33364241, 2020).
colon adenocarcinoma (7 papers, 2017 to 2024). "Immunohistochemical results showed that β-catenin, c-Myc, p-Akt, and Cxcl5 were strongly upregulated in CAC mice colon adenocarcinoma cells compared with normal tissues, whereas anti-S100a9 Ab treatment suppressed their protein levels." (PMID 29326691, 2017). "Notably, CXCL5 expression in colon adenocarcinoma (COAD) and rectum adenocarcinoma (READ) correlated positively with macrophage infiltration." (PMID 39273011, 2024). "In colon adenocarcinoma, CXCL1, CXCL2, and CXCL3 negatively correlated with EMT, while CXCL5, CXCL6, PPBP, and CXCL8 positively correlated with EMT." (PMID 37686093, 2023). "For example, in colon adenocarcinoma, the expression of CXCL1, CXCL2, and CXCL3 negatively correlated with EMT, whereas the expression levels of CXCL5, CXCL6, PPBP, and CXCL8 positively correlated with EMT." (PMID 37686093, 2023).